HOMER2 (homer scaffold protein 2)
Description:
Postsynaptic density scaffolding protein. Binds and cross-links cytoplasmic regions of GRM1, GRM5, ITPR1, DNM3, RYR1, RYR2, SHANK1 and SHANK3. By physically linking GRM1 and GRM5 with ER-associated ITPR1 receptors, it aids the coupling of surface receptors to intracellular calcium release. May also couple GRM1 to PI3 kinase through its interaction with AGAP2. Isoforms can be differently regulated and may play an important role in maintaining the plasticity at glutamatergic synapses. Required for normal hearing. Negatively regulates T cell activation by inhibiting the calcineurin-NFAT pathway. Acts by competing with calcineurin/PPP3CA for NFAT protein binding, hence preventing NFAT activation by PPP3CA.
Synonyms: Homer-2; CPD; Cupidin; Vesl-2; HOMER-2B; HOMER-2A; DFNA68; ACPD
Tractability: Antibody: UniProt places it where antibodies can reach, with medium confidence; its Gene Ontology location is reachable by antibodies, with medium confidence. PROTAC: ubiquitination databases record sites on it; its protein half-life has been measured.
Gene: Protein-coding gene on chromosome 15 (82,834,664 to 82,986,153, reverse strand). Ensembl gene ENSG00000103942.
Subcellular location: Cytoplasm; Cell membrane; Postsynaptic density; Synapse; Cell projection, stereocilium
Subcellular location (Human Protein Atlas): Cytosol
Pathways (Reactome):
Neuronal System: Neurexins and neuroligins
Gene Ontology:
Molecular function: protein binding; G protein-coupled glutamate receptor binding; actin binding; synaptic receptor adaptor activity
Biological process: negative regulation of calcineurin-NFAT signaling cascade; negative regulation of interleukin-2 production; sensory perception of sound; G protein-coupled glutamate receptor signaling pathway; regulation of store-operated calcium entry; regulation of synaptic transmission, glutamatergic
Cellular component: cytoplasm; cytosol; dendrite; plasma membrane; postsynaptic density; stereocilium tip; apical part of cell; glutamatergic synapse; stereocilium; synapse
Genetic constraint (gnomAD): Loss-of-function variants: 23 observed, 35.37 expected, observed/expected ratio (o/e) 0.65, 90% interval 0.47 to 0.92. The upper end of that interval is the gene's LOEUF score, 0.92, which puts it in group 3 of 6, group 1 being the genes least tolerant of losing a copy. Missense variants: 408 observed, 392.89 expected, observed/expected ratio (o/e) 1.04, 90% interval 0.96 to 1.13. Synonymous variants: 148 observed, 150.19 expected, observed/expected ratio (o/e) 0.99, 90% interval 0.86 to 1.13.
Gene-disease validity (ClinGen):
ClinGen rates the evidence that HOMER2 causes each of these diseases.
nonsyndromic genetic hearing loss (autosomal dominant): Moderate.
Homologues: Orthologues: chimpanzee HOMER2 (99% identical), guinea pig HOMER2 (96% identical), pig HOMER2 (96% identical), rat Homer2 (95% identical), mouse Homer2 (94% identical), rabbit HOMER2 (92% identical), dog HOMER2 (85% identical), macaque HOMER2 (84% identical), tropical clawed frog homer2 (74% identical), Drosophila melanogaster homer (45% identical), zebrafish homer2 (23% identical). Paralogues in human: HOMER1 (52% identical), HOMER3 (46% identical).
Diseases named in the same sentence as HOMER2 in open-access papers:
HOMER2 is named in the same sentence as 42 diseases in open-access papers, as found by Europe PMC text mining. Sharing a sentence is not in itself a finding about the gene and the disease. The quoted sentences say what the papers report.
deafness (6 papers, 2020 to 2024). An inherited or acquired condition characterized by the complete loss of the ability to hear from one or both ears. "HOMER2-associated deafness is extremely rare, with the only described variants being p.Arg196Pro, p.Met281Hisfs*9, and p.Pro278Alafs*10." (PMID 39684270, 2024). "These cells expressed several causal genes for various deafness forms, including Eps8l2, Gjb2, Gjb6, Homer2, Coch, Clic5, Dcdc2a, Pou3f4, Col4a6, and Six1." (PMID 37339214, 2023). "HOMER2 function has been associated with deafness, and hearing deficiency is common in MPS patients." (PMID 32050523, 2020). "Our study also highlights the importance of using NGS-based diagnostic methods to identify mutations in low-prevalence deafness genes like HOMER2, thus helping to improve our knowledge about the pathophysiology of DFNA68 and to define more accurate genotype–phenotype correlations in this disorder." (PMID 33809266, 2021). "There were reports that variants in HOMER2 and TMC1 genes may cause autosomal dominant non-syndromic deafness." (PMID 32487028, 2020).
hearing loss (4 papers, 2021 to 2025). "The HOMER2 gene, crucial for synaptic signaling and calcium homeostasis in the auditory system, is linked to sensorineural hearing loss (SNHL), with its variants contributing to severe SNHL in older adults, often necessitating cochlear implants in their 60 s or 70 s." (PMID 40515814, 2025). "HOMER2 is involved in intracellular homeostasis of calcium and cytoskeletal organization and has been previously associated with hearing loss, but its function within the stria vascularis remains unknown." (PMID 35580588, 2022). "So far, 122 genes have been associated with this disorder and 50 of them have been linked to autosomal dominant (DFNA) forms like DFNA68, a rare subtype of hearing impairment caused by disruption of a stereociliary scaffolding protein (HOMER2) that is essential for normal hearing in humans and mice." (PMID 33809266, 2021). "To date, only two different mutations in HOMER2 have been documented to cause hearing loss." (PMID 33809266, 2021).
alcohol use disorder (3 papers, 2015 to 2024). "In this regard, the perturbation in the homeostasis of scaffolding proteins, first and foremost Homer2, has been associated with abnormal neuronal orientation, morphology, and axonal connections, which need to be further investigated in alcohol use disorder, in the early and late life stages." (PMID 29249995, 2017). "Among the Homer isoforms, Homer2 has been shown to be critically important for plasticity in multiple models of alcohol abuse." (PMID 29249995, 2017). "While there are limited data on HOMER1 expression in alcohol use disorder (AUD), most findings focus on HOMER2." (PMID 39518903, 2024). "Homer2 is a member of a family of postsynaptic density (PSD) scaffolding proteins that functions in part to cluster N-methyl-D-aspartate (NMDA) signaling complexes in the PSD, and has been shown to be critically important for plasticity in multiple models of drug and alcohol abuse." (PMID 25755642, 2015).
diabetes (2 papers, 2014 to 2023). "The gene expression of Homer1, Homer2, Homer3, IL-1β, and TNF-α were analyzed by hypertension and diabetes between CAD patients and controls." (PMID 25551602, 2014). "Subgroup analyses of the gene expression of Homer1, Homer2, Homer3, IL-1β, and TNF-α between CAD patients and controls by hypertension and diabetes." (PMID 25551602, 2014).
prostate carcinoma (2 papers, 2016 to 2017). A carcinoma that arises from epithelial cells of the prostate gland. "Notably, one group of genes with very strong negative correlations (≤-0.9) to radiomic features were found to be associated with the AR signaling genes: KLK2, KLK3, HOMER2, BMPR1B, or belong to validated prostate cancer classifiers: CHRNA2, MT1H, DPP4, MYBPC1." (PMID 27438142, 2016).
schizophrenia (2 papers, 2011 to 2020). A major psychotic disorder characterized by abnormalities in the perception or expression of reality. "Patients 2's duplication encompasses 11 OMIM genes, of which RPS17, HOMER2, and ADAMTS3 have already been described as schizophrenia-associated genes in the literature." (PMID 33510659, 2020).
African trypanosomiasis (1 paper, 2025). "KEGG pathway enrichment analysis of these shared genes (corrected p < 0.05) revealed significant overrepresentation in glutamatergic synapse (encompassing HOMER1, HOMER2, PLCB4, and ADCY9) and African trypanosomiasis (containing SELE, MYD88, and PLCB4)." (PMID 41153960, 2025).
Anxiety (1 paper, 2023). Intense feelings of nervousness, tension, or panic often arise in response to interpersonal stresses. "However, we show herein that preventing the CaMKIIα-dependent phosphorylation of Homer2 and dissociation from its interactors is also sufficient to reduce certain signs of anxiety-like behavior in response to acute stressors." (PMID 36973011, 2023). "Thus, phospho-mutations impede dynamic regulation of mGlu5 and its binding partners, with either Pin1 (GRM5AA/AA) or Homer2 (Homer2AA/AA) and produce a similar phenotype as that observed in GRM5R/R mice that cannot bind Homer, suggesting that regulation of mGlu5-Homer scaffolds promotes anxiety." (PMID 36973011, 2023).
anxiety disorder (1 paper, 2023). A category of psychiatric disorders which are characterized by anxious feelings or fear often accompanied by physical symptoms associated with anxiety. "Thus, it will be important in future work to decipher which of these (or other) Homer2 interactions is critical for anxiogenesis of relevance to targeting anxiety disorders." (PMID 36973011, 2023).
Cirrhosis (1 paper, 2021). A chronic disorder of the liver in which liver tissue becomes scarred and is partially replaced by regenerative nodules and fibrotic tissue resulting in loss of liver function. "We tested the expression of Homer2 and Homer3 in peripheral blood in 72 HCC patients, 59 cirrhosis patients, 52 hepatitis B, and 109 control cases." (PMID 33995622, 2021). "We found that Homer2 expression differed significantly between HCC and cirrhosis (P< 0.01), hepatitis B (P < 0.01), and the controls ((P< 0.01)." (PMID 33995622, 2021).
cocaine dependence (1 paper, 2024). A psychologically and socially impaired state, with or without physiological changes, that develops as a result of using cocaine and which leads to compulsive behaviors to acquire the substance. "A prior study examined the association between genetic variants of HOMER1 and HOMER2, located on chromosomes 5q14.2 and 15q24.3, respectively, with cocaine dependence." (PMID 39518903, 2024).
colorectal cancer (1 paper, 2017). A primary or metastatic malignant neoplasm that affects the colon or rectum. "HOMER2 which was identified as a binding partner of MYO18B, interacted with the C-terminal region of MYO18B, a candidate tumor suppressor gene involved in the pathogenesis of human cancers including colorectal cancer." (PMID 29050227, 2017).
endometrioid endometrial adenocarcinoma (1 paper, 2021). "Recently, another study concluded that low-grade endometrioid endometrial adenocarcinoma patients with high expression of Homer2 protein had a better outcome." (PMID 33995622, 2021).
ischemia (1 paper, 2021). A hypoperfusion of the BLOOD through an organ or tissue caused by a PATHOLOGIC CONSTRICTION or obstruction of its BLOOD VESSELS, or an absence of BLOOD CIRCULATION. "We also described the ischemia-associated induction of the novel alternative splicing Homer2 isoform, Homer2e, in CGCs." (PMID 34118975, 2021).
lung carcinoma (1 paper, 2015). "It has been reported that coexpression of HOMER2 with MYO18B enhanced the ability of MYO18B to suppress the anchorage-independent growth of a human lung cancer cell line, suggesting that HOMER2 and MYO18B cooperate in tumor suppression." (PMID 26462029, 2015). "HOMER2 interacts with the C-terminal region of MYO18B, a candidate tumor suppressor gene involved in the pathogenesis of human cancers including lung cancer." (PMID 26462029, 2015).
muscular atrophy (1 paper, 2025). The loss of muscle tissue due to inactivity or disease. "Within this pathway, HOMER1 regulates myofiber differentiation, HOMER2 associates with microgravity-induced muscular atrophy, and ADCY9-mediated cAMP signaling maintains muscle mass and function." (PMID 41153960, 2025).
non-small cell lung carcinoma (1 paper, 2017). A group of at least three distinct histological types of lung cancer, including non-small cell squamous cell carcinoma, adenocarcinoma, and large cell carcinoma. "HOMER2 is known to associate with overall survival and disease-free survival in early stage non-small cell lung cancer." (PMID 29050227, 2017).
otospondylomegaepiphyseal dysplasia (1 paper, 2024). An inborn error of cartilage collagen formation characterized by sensorineural hearing loss, enlarged epiphyses, skeletal dysplasia with disproportionately short limbs, vertebral body anomalies and a characteristic facies. "In the catalog (CD−M7), Pou3f4, Homer2, and Col11a2 were associated with NSHL, Snai2 with Waardenburg syndrome, Lars2 with Perrault syndrome, and Col11a2 with otospondylomegaepiphyseal dysplasia." (PMID 39684410, 2024).
Tinnitus (1 paper, 2021). Tinnitus is an auditory perception that can be described as the experience of sound, in the ear or in the head, in the absence of external acoustic stimulation. "We found that Homer1 expression was upregulated in the auditory cortex of mice with tinnitus, while expression of Homer2 or Homer3 exhibited no significant alteration." (PMID 34546852, 2021). "After establishing a salicylate-stimulated tinnitus mouse model, expression of Homer genes in the auditory cortex was detected and we identified upregulated expression of Homer1, but not of Homer2 or Homer3 in auditory cortex of mice after salicylate stimulation." (PMID 34546852, 2021).
tumor (3 papers, 2015 to 2025). "The expression of Homer2 was associated with tumor differentiation grade and TP level, Homer3 was related to tumor size, tumor nodes and GGT level." (PMID 33995622, 2021). "The expression of Homer2 was associated with tumor differentiation grade (P= 0.012) and total protein (TP) level (P= 0.032)." (PMID 33995622, 2021). "Correlation analysis results showed that Homer2 expression was significantly associated with tumor differentiation grade (P = 0.012) and TP (P = 0.032), while the expression of Homer3 was significantly related to tumor size (P = 0.010), tumor nodes (P = 0.026) and GGT level (P = 0.001)." (PMID 33995622, 2021). "Tumoroids demonstrated upregulation of oncogene-associated genes (Ackr3, Adcy3, Fam222) and downregulation of tumor suppressor genes (Casz1, Frk, Homer2, Pdlim1)." (PMID 40772227, 2025). "In our present study, we found the expression of both Homer2 and Homer3 were downregulated in HCC, which indicated a possible tumor suppressive role of Homer2 and Homer3 in HCC." (PMID 33995622, 2021). "We next explored whether peripheral blood expression level of Homer2 and Homer3 could be used to monitor tumor dynamics." (PMID 33995622, 2021). "The 8 SNPs (CD3EAP rs967591, TNFRSF10B rs1047266, AKT1 rs3803300, C3 rs2287845, HOMER2 rs1256428, GNB2L1 rs3756585, ADAMTSL3 rs11259927, and CD3D rs3181259) were found to be significantly associated with OS and/or DFS when adjusted for age, gender, smoking status, tumor histology, pathologic stage." (PMID 26462029, 2015).
HOMER2 also shares sentences with these, for which no sentence is quoted: cancer (2 papers); infection (2); alcohol (1); Alzheimer disease (1); atherosclerosis (1); Atrophy (1); Bardet-Biedl syndrome (1); brain disorder (1); Cognitive impairment (1); colorectal adenoma (1); congenital diaphragmatic hernia (1); Duane retraction syndrome (1); Hearing impairment (1); hepatitis B (1); Hypertension (1); mammary tumors (1); Obesity (1); Perrault syndrome (1); primary ciliary dyskinesia (1); sarcoidosis (1); Usher syndrome (1); Waardenburg syndrome (1).